APEX1 (apurinic/apyrimidinic endodeoxyribonuclease 1)
Diseases named in the same sentence as APEX1 in open-access papers (continued):
Sharing a sentence is not in itself a finding about the gene and the disease.
breast tumor (3 papers, 2014 to 2025). "Then, in contrast to normal breast tissue, breast tumor tissue had considerably lower MAOB expression levels and higher levels of CYCS, XBP1, HSPA4, APEX1, and SERP1." (PMID 41367017, 2025).
HIV-1 infection (3 papers, 2009 to 2022). The type species of lentivirus and the etiologic agent of acquired immunodeficiency syndrome (AIDS). "In our study, homozygous genotype GG and G allele of APEX1 rs1130409 were found to be significantly associated with increased susceptibility to HIV-1 infection." (PMID 35368687, 2022). "In the analysis of APEX1 rs1130409, genotype GG was associated with increased susceptibility to HIV-1 infection (recessive model: GG vs TT + TG: OR = 1.419, 95% CI = 1.056–1.907, p = 0.020; codominant model: GG vs TT: OR = 1.539, 95% CI = 1.100–2.152, p = 0.012)." (PMID 35368687, 2022). "In this study, we investigated whether seven potentially functional SNPs in the XRCC1 and APEX1 genes are associated with susceptibility to HIV-1 infection and the AIDS progression in men who have sex with men (MSM) populations in northern China." (PMID 35368687, 2022). "Therefore, this study aims to investigate the role of functional polymorphisms of XRCC1 and APEX1 genes in the susceptibility and clinical progression of HIV-1 infection, and to provide a theoretical basis for the prevention and treatment of the disease." (PMID 35368687, 2022). "Associations between APEX1 and XRCC1 gene polymorphisms and susceptibility to HIV-1 infection." (PMID 35368687, 2022). "Importantly, in a siRNA screen targeting DNA repair factors, APEX1 knockdown was found to inhibit HIV-1 infection by more 60%." (PMID 23166591, 2012). "However, the roles of single nucleotide polymorphisms (SNPs) in APEX1 and XRCC1 and their impact on HIV-1 infection and AIDS progression remain unclear." (PMID 35368687, 2022).
systemic lupus erythematosus (3 papers, 2013 to 2024). An autoimmune multi-organ disease typically associated with vasculopathy and autoantibody production. "We also deleted Apex1 in MRL/Mplpr/lpr (Lpr) mice, which are known to develop systemic lupus–like disease involving abnormal activation of Tfh cells, and found that deletion of Apex1 (Lpr-Apex1fl/flCd4Cre) completely inhibited the lupus phenotype." (PMID 39739423, 2024).
ulcerative colitis (3 papers, 2015 to 2024). An inflammatory bowel disease involving the mucosal surface of the large intestine and rectum. "It has been shown that APEX1 controls the inflammatory response in LPS-stimulated macrophages and it is significantly increased in the colonic epithelium of patients with ulcerative colitis." (PMID 28068390, 2017).
autoimmune disease (2 papers, 2021 to 2024). A disorder resulting from loss of function or tissue destruction of an organ or multiple organs, arising from humoral or cellular immune responses of the individual to their own tissue constituents. "We provide further evidence that inhibiting the base repair activities of Apex1 with chemical inhibitors similarly abrogated the induction of autoimmune diseases." (PMID 39739423, 2024). "Clearly, the striking effects of delayed MH treatment in suppressing EAE suggest that Apex1 is a promising therapeutic target in treatment of autoimmune diseases." (PMID 39739423, 2024). "In the present study, we took a multiplicity of approaches to demonstrate that Apex1 is indispensable in the generation of cytopathic T effector cells in models of autoimmune diseases." (PMID 39739423, 2024). "The fact that Apex1 regulates this bifurcation makes Apex1 a promising therapeutic target in multiple autoimmune disease settings." (PMID 39739423, 2024). "Collectively, our study suggests that Apex1 serves as a gatekeeper for the generation of cytopathic T cells and that therapeutically targeting Apex1 may have important clinical implications in the treatment of autoimmune diseases." (PMID 39739423, 2024). "Consequently, Apex1-deleted T cells failed to acquire any effector features after activation and failed to mediate autoimmune diseases and allergic tissue damages." (PMID 39739423, 2024).
cerebral infarct (2 papers, 2017 to 2025). "In a case-controlled study involving 177 patients with cerebral infarction and 309 control subjects, a combined APEX1 rs1760944-rs3136814-rs1130409 SNP was differentially distributed, with a higher prevalence of the G-C-T haplotype in both male and female patients with cerebral infarction." (PMID 40243693, 2025).
chronic cholecystitis (2 papers, 2018 to 2023). "In comparison to gallbladder epitheliums with chronic cholecystitis, the positive rate of APEX1 expression in GBC including SC/ASC and AC was significantly higher (P < 0.001)." (PMID 37283798, 2023). "The chronic cholecystitis tissues with APEX1 positive expression occurred moderate to severe dysplasia, suggesting that APEX1 may be involved in the evolution of benign lesions into GBC." (PMID 37283798, 2023). "Furthermore, the epithelium of chronic cholecystitis with positive APEX1 expression presented moderate to severe dysplasia, indicated that APEX1 could be a biomarker to assess precancerous lesion in gallbladder." (PMID 37283798, 2023). "Then, APEX1 expression in 215 GBC tissues (including 146 ACs and 69 SC/ASCs) and 30 gallbladder epitheliums with chronic cholecystitis was detected by immunohistochemistry." (PMID 37283798, 2023). "Similarly, this study confirmed that APEX1 expression in GBC was significantly higher than that in corresponding adjacent normal tissues and chronic cholecystitis tissues." (PMID 37283798, 2023).
Cirrhosis (2 papers, 2015 to 2019). A chronic disorder of the liver in which liver tissue becomes scarred and is partially replaced by regenerative nodules and fibrotic tissue resulting in loss of liver function. "All showed an up-regulation of APE1/Ref-1 in HCC with HCC/DLC ratio >1, while only 57.8% of subjects presented an up-regulation in cirrhosis as compared to NL indicating that transcriptional up regulation of APEX1 gene is always present in HCC and in more than half of cirrhotic samples." (PMID 26624999, 2015). "Multivariate analysis with other clinicopathological values including age, sex, HBV infection, cirrhosis, histologic grading, and pathologic TNM staging showed that cytoplasmic APEX1 expression in HCC and CC cells is also a predictor of a shorter DFS period (p = 0.009 and p = 0.011, respectively)." (PMID 31375000, 2019).
endothelial dysfunction (2 papers, 2023 to 2025). In vascular diseases, endothelial dysfunction is a systemic pathological state of the endothelium (the inner lining of blood vessels) and can be broadly defined as an imbalance between vasodilating and vasoconstricting substances produced by (or acting on) the endothelium. "PE has been widely characterized by maternal endothelial dysfunction in the placenta, and it has been previously suggested that the dysregulation of endothelial cells caused by hypoxia may be related to the downregulation of APEX1." (PMID 38203356, 2023). "However, the specific involvement of APEX1 in these contexts, especially for congenital and diabetic heart disease or endothelial dysfunction under disturbed flow, has yet to be fully elucidated." (PMID 40243693, 2025).
gallbladder cancer (2 papers, 2018 to 2023). "Although APEX1 is associated with the tumorigenesis and progression of some human cancer types, the function of APEX1 in gallbladder cancer (GBC) is unclear." (PMID 37283798, 2023).
liver cirrhosis (2 papers, 2020 to 2021). "The APEX1 levels were significantly higher in low-AFP expressing HCC patients compared to patients with liver cirrhosis." (PMID 32167932, 2020). "In the GSE63898 dataset, the APEX1 mRNA levels of the HCC tissues were significantly higher than the liver cirrhosis samples." (PMID 32167932, 2020). "Both APEX1 and AFP expression was significantly higher in HCC tissues compared to liver cirrhosis samples." (PMID 32167932, 2020).
malignant peripheral nerve sheath tumor (2 papers, 2023 to 2024). Malignant peripheral nerve sheath tumor (MPNST) is a rare and often aggressive soft tissue sarcoma occurring in a wide range of anatomical sites. "To understand whether the effects of APEX1 KD in retinal endothelial cells are consistent across cell types, we selected four types of cancer cells (PDAC, lung, HeLa, and malignant peripheral nerve sheath tumor (MPNST)) for comparison based on available published datasets." (PMID 36674619, 2023).
neutropenia (2 papers, 2021 to 2024). A decrease in the number of neutrophils found in the blood. "APEX1 c.190A>G has relatively recently been proposed as a candidate gene, which has been revealed to have a strong relation with early onset MP-related neutropenia occurring within 28 days as well as a cumulative incidence of MP-related neutropenia." (PMID 33804051, 2021). "The missense variation rs2307486 (c.190A>G) in APEX1 is strongly related to early onset MP-related neutropenia in pediatric ALL patients." (PMID 33804051, 2021).
preeclampsia (2 papers, 2014 to 2024). Preeclampsia is a hypertensive disorder of pregnancy that is characterized by new-onset hypertension with proteinuria presenting after 20 weeks of gestation, and depending on mild or severe forms may initially present with severe headache, visual disturbances, and hyperreflexia. "A subgroup analyses revealed differences in the allelic frequencies of APEX1 Asp148Glu polymorphism between women with mild preeclampsia and severe preeclampsia (p = 0.035)." (PMID 24619222, 2014). "In the present study we aimed to investigate the association between APEX1 Asp148Glu, XPD Lys751Gln, XRCC1 Arg399Gln and XRCC3 Thr241Met polymorphisms and the risk of preeclampsia in a Mexican population." (PMID 24619222, 2014).
adenoma (1 paper, 2013). A neoplasm arising from the epithelium. "We report a two-fold increased adenoma risk associated with SNP rs17111750 located 5′-upstream of APEX1, only among African-Americans." (PMID 23951112, 2013).
AIDS (1 paper, 2022). A syndrome resulting from the acquired deficiency of cellular immunity caused by the human immunodeficiency virus (HIV). "In conclusion, the present study suggests that the polymorphisms of APEX1 and XRCC1 may increase the risk of HIV-1 susceptibility and the clinical progression of AIDS in MSM populations in northern China." (PMID 35368687, 2022).
Aleutian disease (1 paper, 2024). "From this, we identified several candidate genes contributing to the growth and feed efficiency (ARID1B, APPL1, TOX, and GPC5), reproduction (GRM1, RNASE10, WNT3, WNT3A, and WNT9B), pelt quality (MYO10, and LIMS1), and Aleutian disease tests (IFNGR2, APEX1, UBE3A, and STX11)." (PMID 38167844, 2024).
colonic adenoma (1 paper, 2019). "In both colonic adenoma and adenocarcinoma, APEX1 expression has been shown to be pronounced in the cytoplasm, in contrast to the predominantly nuclear expression in normal colonic epithelial cells." (PMID 31375000, 2019).
colorectal adenoma (1 paper, 2013). An adenoma that arises from the colon or rectum. "However, among Asian-Pacific Islanders we observed two SNPs in FEN1 and one in NTHL1, and among African-Americans one SNP in APEX1 that were associated with colorectal adenoma risk." (PMID 23951112, 2013). "We observed statistically significant associations between colorectal adenoma risk and polymorphisms in the FEN1 gene (two tagSNPs) and NTHL1 gene (one tagSNP) among Asian-Pacific Islanders, and the APEX1 gene among African-Americans (one tagSNP)." (PMID 23951112, 2013).
experimental autoimmune encephalomyelitis (1 paper, 2024). An autoimmune demyelinating disease of the central nervous system that is produced experimentally in animals by the injection of homogenized brain or spinal cord in Freund's adjuvant. "To examine the impact of conditional Apex1 deletion on the induction of immune-mediated diseases, we initially used an experimental autoimmune encephalomyelitis (EAE) model, in which damage to the CNS is mediated primarily by Th1/Th17 effector cells." (PMID 39739423, 2024).
fatty liver (1 paper, 2023). "In the case of APEX1, the TT haplotype significantly increases the risk of fatty liver occurrence, while the GG haplotype decreases it." (PMID 37511066, 2023).
hydronephrosis (1 paper, 2023). Collection of urine in the renal pelvis that results in dilatation of the renal pelvis and calyces. "While more cell types involve DNA damage mechanisms mediated through altered cooperation with APEX1 in the kidney, less is known about how this may contribute to a hydronephrosis phenotype." (PMID 37872881, 2023).
ischemia (1 paper, 2025). A hypoperfusion of the BLOOD through an organ or tissue caused by a PATHOLOGIC CONSTRICTION or obstruction of its BLOOD VESSELS, or an absence of BLOOD CIRCULATION. "A careful examination of in vivo APEX1 expression in rat myocardium revealed that ischemia-reperfusion injury leads to an increase in cytosolic APEX1 abundance and a decrease in nuclear abundance in rat left ventricular wall." (PMID 40243693, 2025).
keratoconus (1 paper, 2023). A degenerative, structural disorder of the eye, characterized by a cone-shaped protrusion of the cornea. "Given the function and existence of variants in APEX1 associated with the keratoconus phenotype, this gene could be a good candidate causal gene." (PMID 37895187, 2023). "Two variants in APEX1 are associated with a risk of keratoconus." (PMID 37895187, 2023).
Pca (1 paper, 2016). "In order to confirm these associations, a sensitivity analysis was performed by removing the studies one by one, which suggested that the APEX1 Asp148Glu polymorphism should be associated with Pca, especially in subjects of Asian descent." (PMID 27248666, 2016). "Associations between the APEX1 polymorphism and the invasiveness of Pca based on the Gleason score, prostate-specific antigen expression and clinical status were also evaluated." (PMID 27248666, 2016). "In this part of the study, we tried to investigate the function of the APEX1 Asp148Glu polymorphism in the development of Pca, on the basis of the Gleason score, prostate-specific antigen expression and clinical status of the cancer." (PMID 27248666, 2016). "Recently, two meta-analyses were conducted that showed a significant association between the APEX1 Asp148Glu polymorphism and Pca, especially among Caucasian subjects and the hospital-based population." (PMID 27248666, 2016). "Combining the features and function of the APEX1 Asp148Glu polymorphism, recent studies and our comprehensive analysis, we suggest that the rs1130409 mutation might increase the risk of developing Pca, especially among Asian subjects." (PMID 27248666, 2016). "Our results suggest that the APEX1 Asp148Glu polymorphism is significantly associated with Pca in subjects of Asian descent as well as in other populations, and might stimulate the development of Pca rather than invasion." (PMID 27248666, 2016).
xeroderma pigmentosum group D (1 paper, 2023). Any xeroderma pigmentosum in which the cause of the disease is a mutation in the ERCC2 gene. "We investigated the role of DNA repair proteins breast cancer susceptibility 2 (BRCA2), xeroderma pigmentosum group D (XPD) and apurinic/apyrimidinic endodeoxyribonuclease 1 (APE1) in determining the risk for head and neck squamous cell cancer (HNSCC) in a case-control study from North-East India." (PMID 37113717, 2023).
cancer (246 papers, 2004 to 2026). A tumor composed of atypical neoplastic, often pleomorphic cells that invade other tissues. "Several studies have reported associations between APEX1 SNPs, such as rs1760944 and rs1048945, and risk of several cancers including prostate." (PMID 35096612, 2021). "Apurinic/apyrimidinic endodeoxyribonuclease 1 (APEX1) is involved in the DNA damage repair pathways and associates with the metastasis of several human cancers." (PMID 33946672, 2021). "APEX1 has been associated with cancer, cardiovascular diseases, and neurodegeneration and seems to play a role in the inflammatory process." (PMID 31375000, 2019). "As far as we know, this study is the latest to report that the APEX1 rs3136817 genotype is associated with cancer risk." (PMID 29720094, 2018). "The high T-score of the D148E mutation in APEX1 suggests that the mutant protein is closer to cancer-related nodes than neutral nodes in the protein interaction network." (PMID 29662108, 2018). "There are several polymorphisms in the APEX1 gene, of which Asp148Glu (rs1130409) has been associated with many cancers." (PMID 27248666, 2016). "Essential roles for mammalian AP endonuclease in telomere maintenance have been reported, which supports the association of APEX1 with cancer development." (PMID 27333808, 2016). "As the most frequently assessed variant, the APEX1 Asp148Glu polymorphism is thought to be associated with many cancers." (PMID 27248666, 2016). "We aimed to summarize available data on the association of the APEX1 Asp148Glu (rs1130409) polymorphism with risk of multiple types of cancer via a meta-analysis." (PMID 24349526, 2013). "Although other sources of heterogeneity cannot be easily ruled out, this study, to the best of our knowledge, is so far the largest meta-analysis examining the association of the APEX1 Asp148Glu polymorphism with cancer risk." (PMID 24349526, 2013). "Homozygosity (TT genotype) for the rs1130409 APEX1 SNP was significantly associated with a poor overall cancer survival." (PMID 23631762, 2013). "Overall and subgroup estimates of the associations of APEX1 Asp148Glu polymorphism with cancer risk under two genotypic models." (PMID 24349526, 2013). "Overall and subgroup estimates of the associations of APEX1 Asp148Glu polymorphism with cancer risk under allelic and dominant models." (PMID 24349526, 2013). "Via a meta-analysis of the data from 58 articles and on 48903 participants, we investigated the association of the non-synonymous polymorphism Asp148Glu in APEX1 with cancer risk." (PMID 24349526, 2013). "There are several lines of evidence supporting an association between the variant APEX1-148 Glu allele and a decreased risk of a number of human cancers." (PMID 22792228, 2012). "Nevertheless, there were also inconsistent reports of an association between APEX1 Asp148Glu polymorphism and cancer risk." (PMID 22792228, 2012). "This polymorphism could alter the structural configuration of the APEX1 protein, reducing its repair efficiency, and has been associated with various cancer types." (PMID 40833230, 2025). "Furthermore, we identified pan-cancer replicated associations of APEX1, RECQL, and DNMT1 with dHRICA (with DNMT1 additionally associating with dHRVAE2)." (PMID 35764656, 2022). "Therefore, the conclusion associated between APEX1 polymorphisms and cancer risk should be specified in a particular cancer type and population." (PMID 31341530, 2019). "As the s-APEX1 level was significantly higher in the HCC, CC, and ccRCC groups than in the healthy control group when the HBV DNA (+) group was excluded, we performed ROC analysis to identify the appropriateness of s-APEX1 as a diagnostic marker for the three cancers." (PMID 31375000, 2019). "Therefore, an active inflammation/immune state and the three cancers need to be separated when the s-APEX1 level is considered to be a diagnostic tumor marker of the three cancers." (PMID 31375000, 2019).